AHR (aryl hydrocarbon receptor)
Diseases named in the same sentence as AHR in open-access papers (continued):
Sharing a sentence is not in itself a finding about the gene and the disease.
tumor (continued). "The tumor-suppressive effect was ascribed to indole-3-lactic acid (ILA), a metabolite of L-tryptophan generated by B. breve lw01, which could activate aryl hydrocarbon receptor (AhR) in macrophages to regulate their differentiation." (PMID 38773969, 2024). "While this is corroborated by the ability of IL4I1 to activate the AhR in various models and the high expression of IL4I1 in cancer tissues, it is argued by another study demonstrating only poor correlation between the expression of IL4I1 and individual AhR target genes in a number of tumor types." (PMID 39211039, 2024). "Whether overexpression of AHR is a positive or negative prognostic factor for cancer patient prognosis depends on the tumor type." (PMID 39450255, 2024). "Furthermore, the endogenous AhR kynurenine is produced through the metabolism of tryptophan by IDO1 which is induced in stromal cells, or by TDO2 which can be up-regulated in tumor cells and the tumor stroma." (PMID 39200369, 2024). "Moreover, AhR mRNA expression was independent of classical clinical parameters, i.e., gender, age, tumor grade, lymphatic invasion, metastasis status, TNM stage, vascular or neural invasion, and the GC subtype." (PMID 39200369, 2024). "However, our research findings that 5-FU can induce effectively immunogenic cell death (ICD) to further treat tumor by activating immune systems, while the secretion of interferon-γ (IFN-γ) re-induce the Kyn-AHR axis activation, leading to poor treatment efficiency." (PMID 38755645, 2024). "Notably, USP14 knockdown upregulates cytotoxic T-cell activity and enhances anti-tumor immunity in CRC by downregulating IDO1 expression without affecting AhR activity, suggesting a potential avenue for CRC-targeted therapy." (PMID 38462620, 2024). "In experimental models, the absence of AHR diminished the tumor-promoting effects of TDO." (PMID 39678512, 2024). "Although the analysis of 43 tumor cores done here may not be sufficient to draw definitive conclusions, the elevated cytosolic AhR expression found in NSCLC compared to that found in the other four cancer types is intriguing." (PMID 38680496, 2024). "The dysregulation of AHR-mediated pathways may disrupt the balance between pro-inflammatory and anti-inflammatory responses, favouring tumour progression and immune evasion but it is still not possible to determine which path is the most important." (PMID 37760608, 2023). "AhR activation by kynurenines could induce the transcription factor FoxP3, promoting the inhibition of cytotoxic effector T cells, such as CD8+ T cells and NK cells, thus allowing tumor cells to escape destruction." (PMID 36986469, 2023). "However, there were no significant changes in the expression levels of AHR signaling pathway-related molecules, including AhR, AhRR, Cyp1a1, Cyp1a2, Cyp1b1 and Cox2, in tumor-infiltrating neutrophils from Arnt−/− mice." (PMID 36859266, 2023). "All these findings, thus, unequivocally suggest that AHR may be tumor suppressive, rather than oncogenic in many types of cancers." (PMID 37151890, 2023). "Using the patient-derived nonembolized tumor primary cell culture, the effects of a hypoxia mimetic cobalt chloride (CoCl2) and an activator of the AhR signaling pathway benzo(α)pyrene (B[a]P) on mRNA levels of HIF-1α, AhR, and their target genes were investigated." (PMID 37305351, 2023). "The AhR has been found to induce the expression of immunoregulatory enzymes and factors such as arginase 1 (Arg1], IDO, IL-10 and the S100 calcium binding protein S100A9 which are important for the immunosuppressive function of TAMCs by creating a tumor-promoting microenvironment." (PMID 37696458, 2023). "Thus, during the hypoxia simulated by means of CoCl2 in patient-derived tumor primary cultured cells, the expression of genes HIF-1α and AhR changed unidirectionally, whereas AhR and CYP1B1 expressions were activated by the inducer (B[a]P) only during the hypoxic state of the cultured tumor cells." (PMID 37305351, 2023).
tumor (continued). "Also presented are the findings about the impact of a hypoxia mimetic (CoCl2) and of an activator of the AhR signaling pathway (B[a]P) on mRNA levels of HIF-1α, AhR, and of their target genes in primary culture of patient-derived nonembolized tumor cells." (PMID 37305351, 2023). "The size of the tumours in Ahr–/– bone-marrow-reconstituted mice was reduced to the same extent as that of tumours from wild-type reconstituted mice after treatment with 3-IAA and FIRINOX, arguing against a role of the AhR in mediating the efficacy of 3-IAA and FIRINOX treatment." (PMID 36813961, 2023). "However, our data show that four to five days of 3-IAA treatment without chemotherapy is not sufficient to affect the growth of the tumour, and only reduces the growth of the tumours via an AhR-independent mechanism when it is combined with chemotherapy." (PMID 36813961, 2023). "Finally, we compared the HIF and AHR composite scores for each individual tumour and found a significant negative correlation between the two composite scores, further supporting an antagonism between the pathways." (PMID 36725335, 2023). "Furthermore, AHR knockdown, similar to MESH1 knockdown, repressed TAZ and proliferative gene expression and inhibited cell proliferation and tumor growth in vivo." (PMID 35273140, 2022). "ELISA detection of inflammation-related factors (INF-γ and TNF-α) further showed that tumor tissues from mice treated with LV-LINC00665 and irradiation presented with decreased levels of INF-γ and TNF-α, which could be reversed additional sh-AhR treatment." (PMID 35918714, 2022). "Controversially, kynurenine signaling through the AhR has been reported to promote the expression of the activating receptors NKp30, NKp46, perforin, and granzyme B in NK cells, which is supported by the observation that IDO1 inhibition impairs NK cell activity against tumor cells." (PMID 36713558, 2022). "Accordingly, this receptor is required to block hepatocarcinogenesis induced by the toxin diethyl nitrosamine, and AhR-lacking mice show increased tumor burden due to expansion of undifferentiated hepatic pluripotent cells that unusually remain in the adult liver even after age-dependent maturation." (PMID 35619220, 2022). "Interestingly, the analysis indicates that CYP1B1 is likely regulated by two different mechanisms because basal CYP1B1 expression is retained even in AhR-low tumours, a feature that is not evident for CYP1A1." (PMID 33809117, 2021). "Although coplanar PCBs seem to play a key role in tumor-promoting effects of PCB mixtures (i.e., Aroclor 1260) through the activation of aryl hydrocarbon receptor (AhR), the non-coplanar fraction of this blend also contributes considerably to its tumor-promotion potential." (PMID 33837873, 2021). "However, its role in carcinogenesis is not clearly defined, and opposite effects of AhR on tumor progression have been reported." (PMID 33499346, 2021). "However, AHR activation does not always necessarily promote cancer as it also exerts tumor-suppressive effects and has been shown to inhibit tumor formation 91-93 and metastasis 94-96." (PMID 34646367, 2021). "Importantly, repopulating tumor cells can escape immune surveillance by transferring to adjacent CD8+ T cells the KYN metabolite, which in turn activates the aryl hydrocarbon receptor (AhR) and increases PD-1 expression." (PMID 34445444, 2021). "Although TDO and IDO2 are not the current focus of this article, researchers should pay close attention to them as targeting tumour dormancy via the Kyn/AhR signalling may not always be IDO1 specific." (PMID 34539663, 2021). "Overall, this non-exhaustive collection of studies shows that AhR activation promotes tumor progression in various types of cancer and that the immunosuppressive properties of the kynurenine-activated AhR constitutes a highly promising axis for cancer treatment." (PMID 33451095, 2021).
tumor (continued). "Indeed, several studies concerning the IDO1/Kyn/AhR metabolic axis argue that IFN-γ is needed only for initiation but not maintenance of tumour dormancy – some other factors have been involved in the consecutive IDO1 activity." (PMID 34539663, 2021). "AhR activation also induces CD39 and CD73, thereby increasing the conversion of ATP to adenosine, allowing AhR activation to raise adenosine levels from different cells of the tumour microenvironment, thereby driving A2Ar activation and contributing to ‘exhaustion’ in NK cells and CD8+ T cells." (PMID 33375613, 2020). "The expression of IDO is sustained by an autocrine loop in the presence of AhR and KYNA in tumor infiltrating tolerogenic DCs and a positive feedback loop controlled by AhR drives IL-6 expression, and it sustains IDO expression and KYN production in tumor cells." (PMID 32012948, 2020). "In addition, Kruppel-like Factor 6 (KLF6); a tumour suppressor through regulation of the p21Cip1 cyclin-dependent kinase inhibitor, has been identified as a novel DNA-binding partner of AhR to express inducible-TCDD when bound at the non-consensus XRE." (PMID 32456012, 2020). "Furthermore, a combination of IDO1 or AhR inhibitors to block this pathway and IFN-β treatment significantly decreased colony size and colony number of tumor cells, due to dormant tumor cells that were abrogated, which provided a novel and ideal treatment against cancer dormancy." (PMID 31297335, 2019). "3MC upregulated the epithelial–mesenchymal transition (EMT) and tumor biomarkers; the models exhibited the reciprocal expression of histone deacetylase 1 (HDAC1) and RhoA, namely increased HDAC1 and decreased RhoA expression, through hypoxia-inducible-factor (HIF)- and AhR-dependent mechanisms." (PMID 30872677, 2019). "Moreover, DC depletion in vivo lowered tumor-infiltrating CD4+ T-cell expression of CD39, CD49b, CD73, AHR, IL-17, and IL-10 in PDA suggesting that, besides driving select cytokine expression, DC promote this Tr1-like surface phenotype in PDA-associated CD4+ T cells." (PMID 30926808, 2019). "In addition, Kyn and Kyn derivatives can bind the aryl hydrocarbon receptor (AhR), which has been shown to impair the proliferation and function of various immune effectors, including CD8+ T lymphocytes, and provide tumor cells with a means to evade anticancer immunosurveillance." (PMID 31511064, 2019). "Inhibitors of the IDO1-Kyn-AhR pathway could abolish the potential negative effects of CAI in the tumor microenvironment." (PMID 31511064, 2019). "Interestingly, the AhR has been shown to act as a critical receptor protein that mediates tumor development independent of exogenous ligands." (PMID 31035533, 2019). "Moreover, by focusing on early primary luminal-like BC (pT1 and pT2 only, tumor size inferior to 5 cm), the same significant correlation of total AhR expression and short OS was observed (p = 0.013, data not shown)." (PMID 30813617, 2019). "However, GSI treatment significantly reduced AhR mRNA expression in CD4+ T cells purified from tumor site (P<0.0001), while slightly decreased AhR expression in CD4+ T cells purified from nontumor site (P=0.006)." (PMID 30473538, 2018). "Whether the tumour suppressor activity of AHRR is dependent or not on its ability to inhibit AHR is not fully understood." (PMID 28681081, 2018). "However, AHR is not lost or repressed in tumors, thus indicating that AHR is not a canonical tumor suppressor." (PMID 30254109, 2018). "Interestingly, IL-22 production and IL-22/AhR mRNA was significantly elevated in lung-resident CD4+ T cells from tumor site in comparison with those from nontumor site (all P<0.0001)." (PMID 30473538, 2018). "In addition, immunoblot analyses exhibited an elevated activation of STAT3 (phosphorylation at Y-705), an established key driver of UVB-induced SCC development, in tumor samples from both, AHR+/+ and AHR−/− mice, as compared to irradiated non-lesional skin." (PMID 30013037, 2018).
tumor (continued). "However, several downstream AHR transcriptional targets, such as CYP1B1, ALDH and GST genes were found to be significantly reduced with more than two-fold differences observed between tumours and controls." (PMID 28649092, 2017). "AHR acts as a modulator in both SP and non-SP cells during primary tumor growth." (PMID 27129165, 2016). "Furthermore, AhR was methylated in 33% of primary human ALL tumors, suggesting that AhR silencing in this tumor type could hamper the likely tumor suppressor activity of this receptor." (PMID 27243009, 2016). "BBP may specifically activate the oncogenic AHR gene cluster while inhibiting or not influencing the tumor-suppressive AHR gene cluster." (PMID 27129165, 2016). "In addition, IDO could promote tumor cell survival and motility via production of endogeneuos KYN that drive the activation of aryl hydrocarbon receptor in cancer cells." (PMID 27613847, 2016). "However, Aldh1a1 downmodulation in AhR-expressing B16F10 cells did not significantly affect tumor growth in vivo." (PMID 26242870, 2015). "We previously demonstrated that merely reducing AhR expression altered cell proliferation, anchorage independent growth, migration and apoptosis in MDA-MB-231 cells in vitro, and reduced orthotopic xenograft tumor growth and experimental pulmonary metastasis in vivo." (PMID 24932473, 2014). "Moreover, the AhR pathway, which involves HIF-1β (ARNT), is known to mediate anti-tumor effects." (PMID 25068796, 2014). "Although the precise mechanisms behind metabolic and tumor-generating effects of dioxins have not been elucidated, AhR-mediated circadian clock disruption by AhR ligands in central and peripheral tissue, as suggested by the current review, may be important." (PMID 24987953, 2014). "It is possible that the effects via the AHR, including IDO induction and Treg generation actually outweigh some of the anti-cancer effects of the drug, as it is postulated that cancer cells utilize IDO and its regulation to prevent their destruction by immune mediators of tumor surveillance." (PMID 22970246, 2012). "Taken together, these results highlight that altered expression of endogenous AhR that is not activated by exogenous ligand has, in general, pro-proliferative and tumor-promoting properties, whereas exogenously activated AhR can have anti-proliferative activities." (PMID 20565777, 2010). "However, we did not observe a correlation between AhR expression in the tumor cells and disease recurrence (data not shown)." (PMID 20140206, 2010). "Therefore, it appears either that the AhR is not involved in suppressing proliferation or that AhR inhibition is not sufficient to block proliferation of this relatively advanced tumor cell line." (PMID 16569260, 2006). "A recent study reported that AhR activity suppresses STImulator of Interferon Genes (STING) mediated type I interferon (IFN-I) expression in TNBC cell lines and that AhR could potentially represent a feasible therapeutic strategy to enhance the immunogenicity of TNBC tumours." (PMID 40646277, 2025). "However, tumor cells may inhibit STING levels and IFN-I production by increasing the expression of tryptophan metabolites or high expression of the aromatic hydrocarbon receptor AhR, enhancing patient resistance." (PMID 38753689, 2024). "Meanwhile, CISE‐PFD@Gel‐treated Renca renal carcinoma tissues also exhibited significantly lower AhR expression and showed better inhibition efficacy than that of the CISE@Gel group, which may be attributed to PFD‐elicited TPME normalization promoted more CISE NPs to be phagocytosed by tumor cells." (PMID 38884220, 2024). "Although this may partially be compensated for by the considerably higher AhR-activating potency of indole-3-pyruvic acid compared to IDO1-generated metabolites, it remains unclear whether IL4I1 is capable of achieving significant AhR activation in most tumor types." (PMID 39211039, 2024).
tumor (continued). "Furthermore, recent studies have identified multiple additional pathways through which ARNT may contribute to tumor initiation, progression, and drug resistance, including the fibronectin/integrin β1/FAK, Myc/Miz/CDKN2B, NF-κB, p38α-MAPK, and canonical AHR/ARNT signaling pathways." (PMID 39684472, 2024). "Finally, AHR antagonists may be considered for tumor therapy once they are guaranteed to not impair gut barrier function and immunity." (PMID 37394584, 2023). "Since the SASP can contribute to tumor development producing proinflammatory cytokines, growth factors and extracellular matrix remodelers that facilitate the expansion of transformed cells, we suggest that the SASP factors in AhR−/− liver could contribute to their enhanced hepatocarcinogenesis." (PMID 35619220, 2022). "Cancer cells may target a number of factors that act to regulate the mitochondrial melatonergic pathway in tumor microenvironment cells, including tryptophan uptake, 14-3-3 isoforms, TPH1/2, serotonin uptake/metabolism, acetyl-CoA, AANAT, ASMT, P2Y1r and mGluR5 receptor, as well as the AhR." (PMID 36613754, 2022). "Moreover, tumor tissues from mice treated with PC9/LV-LINC00665 and irradiation presented with an increased rate of ki67-positive cells and a decreased rate of TUNEL-positive cells, which could be reversed by additional AhR knockdown." (PMID 35918714, 2022). "The reciprocal negative interactions of melatonin and the AhR, coupled to the circadian rhythm of the AhR, would indicate that suppressed melatonin will significantly modulate the levels and effects of the AhR in the tumour microenvironment over the circadian rhythm." (PMID 33375613, 2020). "Therefore, AHR expression may play an either positive or negative role in tumor development based on different cell types." (PMID 29212263, 2017). "Furthermore, in vivo results showed no tumour colonies in AhR overexpressing CL1-5 cells." (PMID 28195146, 2017). "However, the relationship between AhR and tumor progression is not clear." (PMID 19371443, 2009). "To further investigate the common AHR target genes in the tested HCC cells, we conducted differential gene expression (DEG) analysis by comparing tumor cell lines with or without AHR activation." (PMID 40248203, 2025). "Nevertheless, in mouse and human tumor intestinal epithelia, Kyn has been shown to promote β-catenin activity via a PI3K–AKT–GSK3β signaling event, not by AhR-mediated transcriptional activity." (PMID 37232717, 2023). "We found that AHR and p-PYGL were more highly expressed in tumor tissues from nonresponders than in responders after chemotherapy." (PMID 38099490, 2023). "When the cultured tumor cells were treated with 1 μM B[a]P, there were no changes in mRNA expression of HIF-1α, its target genes, ARNT, AhR, and its target gene CYP1B1." (PMID 37305351, 2023). "However, it is of note that NAS and AhR-induced CYP1B1 accumulation in the mitochondria of tumor cells induces apoptosis, indicating that the suppression of NAS mitochondrial efflux may be another important modulator of mitochondrial melatonergic pathway effects in tumor cells." (PMID 37970210, 2023). "Bioprecursor and prodrug approaches that rely on tumour-expressed CYP1A1 and not AhR induction for bioactivation includes our own work focused on reengineered duocarmycin molecules." (PMID 33809117, 2021). "AhR and its nuclear translocator ARNT are expressed in most if not all cells and tissues of the body, including immune and tumor cells." (PMID 31481962, 2019). "Exposure to I3C diet for 2 weeks prior to AOM/DSS treatment sufficed to correct the expression of Znrf3 and Rnf43 in an AHR-dependent manner, as mice lacking Ahr in IEC did not upregulate these tumor suppressors." (PMID 30119997, 2018). "In recent years, AHR has also been reported to exert positive or negative effects on epithelial–mesenchymal transition (EMT), the crucial step in tumor malignant progression." (PMID 27752740, 2017).